APOM (apolipoprotein M)
Diseases named in the same sentence as APOM in open-access papers (continued):
Sharing a sentence is not in itself a finding about the gene and the disease.
Sepsis (continued). "In the baboon sepsis model, the decrease in plasma S1P was observed at earlier time‐points than the decrease in apoM, indicating that the S1P‐apoM interaction is dynamic and the molecules have distinct clearance pathways." (PMID 26990127, 2016). "In conclusion, our results demonstrate that S1P and apoM are strongly reduced in both human and non‐human primate sepsis, the degree of decrease in concentration reflecting the severity of the disease." (PMID 26990127, 2016). "In the human sepsis cohort, previously studied for apoM, plasma demonstrated disease‐severity correlated decreased S1P levels, the profile mimicking that of plasma apoM." (PMID 26990127, 2016). "This function of apoM is likely impaired during the sepsis, which would add to the decreased antioxidative capacity of HDL that is additionally caused by the decrease in PON-1 levels." (PMID 22512779, 2012). "We find that, in response to severe sepsis and SIRS of other causes, the plasma levels of apoM demonstrate a decrease, which is more pronounced than those of apoAI and apoB." (PMID 22512779, 2012). "In a pilot study including six patients with sepsis, the plasma concentration of apoM, estimated by semiquantitative Western blotting, was found to be decreased to around 60%, as compared with the apoM levels after recovery." (PMID 22512779, 2012). "The aim of this study was to investigate the apoM concentration in plasma in a large cohort of patients with sepsis and SIRS." (PMID 22512779, 2012). "Such a theragnostic approach could involve novel carriers of S1P like the ApoM-Fc fusion protein that already demonstrated beneficial effects in a murine sepsis model." (PMID 39524325, 2024). "In addition, several studies have provided evidence regarding the beneficial role of APOM, with its main ligand S1P, in severe inflammatory contexts, including sepsis, heart failure, auto-immune diseases and cancers." (PMID 39303980, 2024). "Studies documented that both HDL and ApoM are reduced during sepsis." (PMID 36915826, 2023). "Similar to HDL, ApoM levels were also shown to be reduced during sepsis and severe inflammation." (PMID 36915826, 2023). "A significant correlation was observed between S1P decline and apoM during sepsis." (PMID 37746079, 2023). "Thus, apoM and S1P plasma levels are decreased in sepsis and dengue fever both affecting vascular permeability." (PMID 36335116, 2022). "The apoM-S1P complex was found to play a central role in numerous inflammatory and lipid metabolism disorders, including hepatic diseases (liver fibrosis, hepatic infections and sepsis, steatohepatitis, liver injury, and HCC)." (PMID 35158806, 2022). "Plasma APOM has previously been suggested to be a biomarker for sepsis." (PMID 31964768, 2020). "The aim of this study was to evaluate changes in S1P and its carrier protein apoM during sepsis." (PMID 26990127, 2016). "Importantly, the decrease in S1P and apoM observed in the baboon sepsis model, which is based on induction of acute bacteraemia, mimicked that observed in the human cohort, where a natural disease progression occurred." (PMID 26990127, 2016). "However, in patients with severe sepsis, S1P was distributed equally between apoM and albumin, indicating that during sepsis S1P is mainly lost from apoM." (PMID 26990127, 2016). "As a carrier for barrier-protective S1P in HDL, the decrease in apoM could contribute to the increased vascular leakage observed in sepsis and SIRS." (PMID 22512779, 2012). "The aim was to determine the plasma concentrations of apoM during sepsis and systemic inflammatory response syndrome (SIRS) and correlate them to levels of apolipoprotein A-I (apoA1), apolipoprotein B (apoB), HDL-, and low-density lipoprotein (LDL)-cholesterol." (PMID 22512779, 2012).
Sepsis (continued). "In an experiment on sepsis in humans and baboons, it was observed that S1P levels were lower in most septic groups, when compared to normal controls, less by almost 46% in severe septic shock, and a homogeneous distribution of S1P was observed between apoM and albumin." (PMID 37746079, 2023). "Moreover, to study in more detail the changes in S1P and apoM during disease progression in sepsis, we have used archived samples from a well‐characterized non‐human primate model of sepsis and analysed factors contributing to alterations in plasma levels of S1P." (PMID 26990127, 2016). "During sepsis and SIRS, the plasma concentrations of apoM decrease dramatically, the degree of decrease reflecting the severity of the disease." (PMID 22512779, 2012). "In the three sepsis groups, the lowest apoM levels were found in the group with severe sepsis and shock, followed by the severe sepsis group without shock and the sepsis group." (PMID 22512779, 2012). "The pronounced decrease in apoM levels in patients with severe sepsis, and also in those with SIRS without infection, suggests that apoM may be a useful marker for severity of disease and prognosis." (PMID 22512779, 2012).
dyslipidemia (20 papers, 2013 to 2025). "While adiponectin is a key adipokine in preventing metabolic syndrome and associated pathologies, much less is known about apoM, especially regarding its expression in adipocytes." (PMID 38491190, 2024). "We also reported a downregulation of AT APOM with obesity, metabolic syndrome, and T2D which are metabolic states associated with low-grade systemic and AT inflammation." (PMID 39303980, 2024). "Analysis of the proteomic profiles of 274 participants from the Qatar Biobank database showed reduced levels of HDL-related apolipoproteins (ApoM and ApoD) in patients with dyslipidemia and concomitant vitamin D deficiency." (PMID 39518736, 2024). "We identified non-synonymous mutations e.g., in ApoM, Notch4, Slc39a7, Smim29 genes and other variations in or near genes associated with metabolic syndrome in human genome-wide association studies." (PMID 36014934, 2022). "It was reported that SNPs in the proximal promoter region of the ApoM gene are associated with dyslipidemia." (PMID 33830664, 2021). "Blood levels of apoM and adiponectin were then considered according to other disease conditions, including T2D, dyslipidemia, and hypertension." (PMID 38491190, 2024). "We previously identified APOM as an adipokine whose gene expression in AT is lower in individuals with obesity, metabolic syndrome, or T2D, compared with healthy ones." (PMID 39303980, 2024). "The APOM gene expression in the AT is lower in individuals with metabolic syndrome, obesity, or T2D." (PMID 39303980, 2024). "ApoM concentration was found to be higher in participants with dyslipidemia, consistent with previous studies." (PMID 38491190, 2024). "APOM expression was inversely correlated with adipocyte size in adipose tissue, lower in obese than in lean individuals, and lower in patients with metabolic syndrome and T2D." (PMID 34093440, 2021). "Plasma proteomic analyses have confirmed significantly reduced apoM levels in MASLD patients, suggesting that disease-related dyslipidemia may be partly attributable to apoM deficiency." (PMID 41303567, 2025). "Accordingly, blood levels of apoM are reduced in obesity, metabolic syndrome, and T2D." (PMID 38491190, 2024). "However, our studies with WD-induced dyslipidemia mice demonstrated that a considerable amount of apoM-bound S1P was distributed to VLDL/LDL and HDL particles." (PMID 32872588, 2020). "A second class consisted of carrier proteins such as apolipoprotein M (APOM), apolipoprotein C1 (APOC1), and clusterin (CLU), which play important roles in cholesterol metabolism and are likely to be associated with cirrhosis‐related dyslipidemia due to reduced liver biosynthesis capacity." (PMID 30824564, 2019). "Hyperlipidemia is often accompanied with complex dyslipidemia, such as elevated very low-density lipoprotein cholesterol (VLDL-C) and LDL-C levels and low high-density lipoprotein cholesterol (HDL-C) levels, which are associated with serum apolipoprotein M (apoM)." (PMID 28877724, 2017). "Unlike adiponectin, apoM levels were lower in participants with hypertension, while they were higher in subjects with dyslipidemia than in the individuals without these conditions." (PMID 38491190, 2024). "The model included apoM and adiponectin as potent explanatory variables, along with BMI, waist circumference, physical activity, TG, HDL-C, hs-CRP, γ-GT, apoC-III, apoB100, T2D, dyslipidemia, hypertension, and case-control status." (PMID 38491190, 2024). "Recently, apolipoprotein M (APOM) gene has been reported relevant to CAD and dyslipidemia." (PMID 24040766, 2013). "Interestingly, the relationship between apoM and dyslipidemia status was no longer observed when only the treated patients (the majority of whom were on statin treatment) were considered among the subjects with dyslipidemia." (PMID 38491190, 2024). "Decreased ApoM has not been reported in PCOS previously and, in this context, may contribute to the increased atherogenic dyslipidemia seen in PCOS." (PMID 36980195, 2023).
Obesity (19 papers, 2004 to 2026). Accumulation of substantial excess body fat. "First, the APOM gene expression in AT was negatively correlated to plasma CRP in individuals with overweight or obesity, indicating that adipose APOM is inversely associated with obesity-related low-grade systemic inflammation." (PMID 39303980, 2024). "Plasma APOM is lower in individuals with obesity compared with lean patients, negatively associated with waist circumference and lower in T2D compared with glucose-tolerant individuals." (PMID 39303980, 2024). "Overall, our study highlights the relationship between APOM and obesity-associated low-grade inflammation and proposes adipose-derived APOM as a novel and local protective factor against AT inflammation." (PMID 39303980, 2024). "The apolipoprotein M (APOM) is an adipokine whose expression is low during obesity and associated with a metabolically healthy AT." (PMID 39303980, 2024). "To further study the association between apoM and IR, we examined the changes in circulating apoM after SG in patients with obesity and analyzed their correlation with the improvement in HOMA-IR." (PMID 38491190, 2024). "ApoM-deficient mice (apoM-KO) are protected against diet-induced obesity and have improved glucose tolerance." (PMID 36335116, 2022). "Our results suggested that rs805296 and 724-del minor allele of ApoM gene, interaction of rs805296 and obesity, rs805297-C and rs9404941-C alleles haplotype were indicators of high T2DM risk." (PMID 32398715, 2020). "In conclusion, rs805296 and 724-del minor allele of ApoM gene, rs805296-obesity interaction, and the alleles rs805297-C and rs9404941-C were risk factors for the development and progression of T2DM." (PMID 32398715, 2020). "After covariates adjustment, GMDR analysis was performed to analyze the correlation of ApoM gene and obesity interaction with the risk of T2DM." (PMID 32398715, 2020). "Given that people with class 3 obesity (BMI > 40 kg/m2) often present kidney disease that could be alleviated after SG, one might expect an increase in plasma apoM levels associated with improved renal function." (PMID 38491190, 2024). "In 300 individuals with obesity, AT APOM mRNA level was negatively associated with plasma hs-CRP." (PMID 39303980, 2024). "To investigate the relationship between these two proteins and IR, we examined whether weight-reduction surgery in patients with obesity (cohort B) could influence the levels of apoM and its association with IR." (PMID 38491190, 2024). "ApoM deficiency was associated with an increased brown adipose tissue content, acceleration of postprandial triglyceride clearance, and protection against diet-induced obesity." (PMID 34093440, 2021). "Furthermore, we studied the interaction of ApoM gene and obesity on risk of T2DM in this case-control study." (PMID 32398715, 2020). "We performed studies in DIO mice because it is a well-described model of prediabetes, impaired glucose tolerance, and obesity, pathologies known to reduce ApoM." (PMID 40579057, 2025). "The link between apoM and obesity has been extensively investigated and a recent study reported that APOM is expressed in human subcutaneous and visceral adipose tissue, predominantly by adipocytes." (PMID 41303567, 2025). "We compared the gene expression of adiponectin and apoM in human subcutaneous AT from individuals with overweight or obesity (cohort C)." (PMID 38491190, 2024). "Then we aimed to explore the role of the adipose-derived APOM on AT during an obesity-induced inflammation." (PMID 39303980, 2024). "Circulating apoM and adiponectin were examined in 169 men with overweight in a cross-sectional study, and 13 patients with obesity during a surgery-induced slimming program." (PMID 38491190, 2024). "ApoM deficiency in mice is associated with increased vascular permeability, brown adipose tissue (BAT) mass and activity, and protection against obesity." (PMID 36335116, 2022).
Obesity (continued). "In a study on non-diabetic individuals (n=79), overweight individuals (n= 32), and individuals with obesity (n= 10), the plasma apoM levels were inversely correlated with BMI, and the PCSK9 levels were positively correlated with insulin levels." (PMID 34093440, 2021). "Lastly, in individuals with obesity, calorie restriction promoted adipose APOM expression and secretion from adipose tissue explants." (PMID 34093440, 2021). "For example, ApoM-S1P has a major influence on diet-induced obesity and postprandial triglyceride metabolism." (PMID 31791242, 2019). "Among these, regression analysis found four well-established obesity associated genes that were positively correlated (CPE, LEP, NPY1R, and NPY5R), and two genes (APOM, and CRP) that were negatively correlated with weight gain." (PMID 23544116, 2013). "APOM, APOA2, APOC3, and APOA1, all apolipoproteins, were associated with lipid transport and involved in the PPAR signaling pathway and cholesterol metabolism, which played important roles in obesity development." (PMID 40438591, 2025). "We previously reported a negative association between AT APOM mRNA level and adipocyte size in women with obesity." (PMID 39303980, 2024). "We tested in vivo whether overexpressing APOM while promoting obesity could limit obesity-induced inflammation development in AT." (PMID 39303980, 2024). "Our study highlights the protective role of adipocyte APOM against obesity-induced AT inflammation." (PMID 39303980, 2024). "In fact, apoM and S1P plasma levels were increased in mice with diet induced obesity." (PMID 37628901, 2023). "ApoM deficient mice exposed to a HFD had lowered plasma S1P levels and higher blood glucose levels, suggesting that apoM-knock-out (KO) mice were less tolerant of HFD-induced obesity." (PMID 37628901, 2023). "However, apoM/S1P complex could also induce obesity by negatively regulating brown adipose tissue activity." (PMID 37628901, 2023). "Interestingly, S1P and apoM may also be affected in contradictory manners in individuals with obesity." (PMID 34093440, 2021). "However, the impact of gene- environment interaction between ApoM gene and obesity onT2DM risk was not studied in Chinese population until now." (PMID 32398715, 2020). "The APOM and ADIPOQ gene expression were measured in the adipose tissue from 267 individuals with obesity and a human adipocyte cell line." (PMID 38491190, 2024). "These may suggest that apoM is related to the initiation and progression of MODY3 and/or obesity." (PMID 15461812, 2004). "The apoM levels correlated positively with PCSK9 levels in lean individuals (r= 0.337, P= 0.041) after adjustment for BMI and apoB, but not in individuals who were overweight or had obesity, suggesting that LDL-associated apoM may be differently processed depending on metabolic health." (PMID 34093440, 2021).
COVID-19 (16 papers, 2021 to 2025). A disease caused by infection with severe acute respiratory syndrome coronavirus 2. "Apolipoproteins APOA1, APOA2, APOL1, and APOM, which have been previously reported to be associated with macrophage and decreased in COVID-19 patients, were all downregulated in the CSF from the eight COVID-19 patients." (PMID 34956212, 2021). "In fact, serum S1P and apoM appear associated with COVID-19 severity and morbidity, due to their role in endothelial barrier dysfunctions, altered immune response, and persistent excessive inflammation in COVID-19 patients." (PMID 35625805, 2022). "The authors tested if SGLT2i (dapagliflozin [Dapa]) increases ApoM in mice using lipopolysaccharide (LPS) and in humans with COVID-19." (PMID 40579057, 2025). "Dysregulation of serum APOL1 and APOM has also been reported in COVID-19 patients." (PMID 36859478, 2023). "Apolipoprotein A1 (APOA-I) and Apolipoprotein M (APOM) are significant in severe COVID-19 cases." (PMID 36677438, 2023). "However, our results show that apolipoprotein D (APOD) and APOM levels were reduced in COVID-19 survivors 6 months after discharge." (PMID 35288537, 2022). "In addition to ApoA-I, most of the apolipoproteins classically associated with HDLs were less abundant in COVID-19 HDL particles, including ApoA-II, ApoC-I, II, III, IV, ApoA-IV, ApoC-I, ApoJ, Apo(a), ApoE, ApoM, ApoD, ApoB100 and ApoF." (PMID 33504824, 2021). "Recent studies have shown that APOM is downregulated in severe COVID-19 patients." (PMID 34093642, 2021). "Recently, blood SPL concentrations have been correlated with COVID-19 severity in humans and animal models: blood concentrations of S1P, total HDL, ApoM, and the ratio of ApoM- versus albumin-bound S1P may be some of the most reliable predictors of COVID-19 morbidity and mortality." (PMID 40386785, 2025). "We also found abnormalities in apolipoprotein levels in COVID-19 survivors 6 months after discharge; specifically, apolipoprotein D (APOD) and apolipoprotein M (APOM) levels were demonstrated to be reduced." (PMID 35288537, 2022). "HDL ApoM-S1P has not been measured directly in pediatric COVID-19, but low circulating apoM and S1P in adult COVID-19 predict both disease severity and mortality." (PMID 36312284, 2022). "In particularwe observed a decrease in the HDL components APOA4 and APOC1 in both COVID-19 non-ICU and ICU/F patients (cluster 3) while APOA2, APOD, APOH, APOM and the HDL-associated PON1 protein appear to be decreased mainly in COVID-19 non-ICU patients (cluster 7)." (PMID 36348270, 2022).